CDK6 (cyclin dependent kinase 6)
Diseases named in the same sentence as CDK6 in open-access papers (continued):
Sharing a sentence is not in itself a finding about the gene and the disease.
breast cancer (continued). "In particular, one SNP pair, rs561681 (DLC1) and rs3731343 (CDK6), was identified to have a synergistic effect on breast cancer patient survival, as verified in two independent cohorts, and these SNPs were each associated with the expression of the corresponding gene." (PMID 25425654, 2014). "Interestingly, p16 was previously shown to inhibit the migration and invasion of breast cancer and other cells in a manner dependent on its interaction with Cdk6." (PMID 23894465, 2013). "These compounds have some common targets but have also been demonstrated to have distinct biological effects on breast cancer cells and the relatively high concentrations necessary to inhibit the expression of CDK6 and to induce cell cycle arrest in breast cancer (from 50 to 200 μM)." (PMID 21435243, 2011). "Moreover, loss or inactivating mutations in the FAT1 tumor suppressor gene, which normally inhibits Hippo signaling, led to the enrichment of YAP/TAZ transcription factors on the CDK6 promoter, ultimately causing CDK6 amplification and resistance to CDK4/6is in ER+ breast cancer." (PMID 40244377, 2025). "This is relevant given that breast cancer cell lines have been associated with CDK4 gene dependency, while hematologic cell lines (i.e., that may be associated with neutropenia or other cell count abnormalities) were associated with CDK6 gene dependency." (PMID 37366894, 2023). "While CDK6/cyclin D3 is linked to the hematopoietic system and is crucial for healthy thymus development and the maturation of bone marrow hematopoietic stem cells, CDK4/cyclin D1 is related to cell proliferation and is essential for supporting the progression of breast cancer." (PMID 37759823, 2023). "In a genomic analysis of breast cancers that were resistant to CDK4/6 inhibitors, loss-of-function mutations were found in the FAT1 gene, and the knockout of FAT1 conferred resistance to CDK4/6 inhibitors by the overexpression of the CDK6 protein via the suppression of the Hippo pathway." (PMID 35681048, 2022). "Notably, among those genetic alteration events whose loss enhances CDK4/6i sensitivity, CDK6, CCND3, CCNE1 and E2F3 were frequently amplified in the genomes of breast cancer patients, whereas among the genes whose loss promotes resistance, RB1, REXO2, PPP2R2A and STT3A were mainly depleted." (PMID 34508104, 2021). "After a prolonged exposure to CDK4/6 inhibitor LY2835219, a significant amplification of CDK6 was found in several breast cancer cell lines, and this may account for a decreased CDK4/6 targeted phosphorylation of Rb1 and a decreased sensitivity of breast cancer cells to CDK4/6 inhibitor." (PMID 34123801, 2021). "Thus, CDK4 and CDK6 represent valuable therapeutic targets of ER+ advanced breast cancer." (PMID 30518851, 2018). "However, the role of cyclin D1/CDK4/CDK6 in breast cancers is highly controversial." (PMID 23886499, 2013). "Cellular experiments confirmed that DSN1 promotes breast cancer proliferation by affecting cell cycle pathways, involving key molecules such as CCNB1, CCND1, CKD1, CDK4, and CDK6." (PMID 41640445, 2026). "Several biomarkers have been proposed in breast cancers, where the field is more advanced, and include up-regulations of the inhibited kinases CDK4 and CDK6 and their partner cyclin D as well as the main target of phosphorylation, RB." (PMID 40699853, 2025). "Abemaciclib hindered MCF-7 and MDA-MB-231 breast cancer cell growth and enhanced RT by inducing cell cycle arrest through the inhibition of CDK4 and CDK6 expression and increasing apoptosis." (PMID 40035822, 2025).
breast cancer (continued). "In breast cancer, lncRNA YIYA interacts with CDK6, enhancing CDK6-dependent PFKBP3 phosphorylation, resulting in the promotion of glycolysis, cell proliferation, and tumor growth." (PMID 41361062, 2025). "The gene expressions of CDK4, CDK6, TGF-β, and NF-κβ were significantly reduced by abemaciclib in breast cancer cell lines MCF-7 and MDA-MB-231 compared to untreated cells of each cell line." (PMID 40035822, 2025). "The aberrant activity of the Ras/MAPK pathway has been identified as pivotal in the initiation and progression of breast cancer, miR‐21's targeting of key activators within this pathway, including ABCB1, AR, CDK6, CSF1, EREG, MKDR, among others." (PMID 40567015, 2025). "Recently, a clinical investigation demonstrated an inverse correlation between CDK6 overexpression and PFS in ER+ breast cancer patients undergoing CDK4/6i therapy." (PMID 40244377, 2025). "In breast cancer, CDK1, CDK5, and CDK20 are overexpressed, while CDK2 and CDK6 are decreased, with high expression correlating with poor prognosis." (PMID 39567714, 2024). "CDK6 is a clinically important target, since CDK4/6 inhibitors are used in treatment of ER+ breast cancer, and clinical trials are currently evaluating their effectiveness in TNBC." (PMID 39171293, 2024). "Further exploration of the CPTAC database discovered that the protein levels of CDK6 were remarkably higher in TNBC than in normal tissue and other subtypes of breast cancer." (PMID 37983610, 2024). "Although CDK4/6 inhibitors for breast cancer have achieved remarkable clinical success, the specific mechanisms of how CDK4 and CDK6 affect tumor micro-environment (TME) and anti-tumor immunity are still poorly understood." (PMID 37833461, 2023). "SKACP003-treated breast cancer cells showed decreased expression of Wnt/β-Catenin targeting genes such as C-Myc, P68, and COX-2 and significant downregulation of CDK-4 and CDK-6 genes." (PMID 36770598, 2023). "Our results show that, by interacting with CDK6, CCNI promotes the proliferation of breast cancer cell lines, unraveling a new pathway that contributes to cell cycle regulation and tumorigenesis." (PMID 37081792, 2023). "ON123300, a multi-kinase inhibitor with high specificity for CDK4/CDK6 and NUAK1, showed a strong anti-tumorigenic effect on breast cancer, glioblastoma, lymphoma, and multiple myeloma and reduced Akt phosphorylation." (PMID 38135881, 2023). "To offer a glimpse into future clinical applications, we analyzed the gene expression of Pal targeted genes, CDK4 and CDK6, and Nif targeted genes STAT3 and CDK2 in breast cancer through the TNMplot database." (PMID 37752122, 2023). "Although the importance of CDK6 in CDK4/6i resistance is widely recognized, the mechanism of CDK6 overexpression remains largely unclear, especially in tumors other than breast cancer." (PMID 37452037, 2023). "It has been shown that miR-6775-3p can negatively regulate CDK4, CDK6, MMP17, and MMP24 levels in breast cancer cells by binding to the 3′UTR of their mRNAs, thereby inhibiting the proliferation, migration, and invasive abilities of breast cancer cells." (PMID 35891968, 2022). "Palbociclib, originally indicated for breast cancer, underwent several phase-I trials on relapse and refractory ALL (NCT03472573, NCT04996160, and NCT03132454) due to its activity on CDK6." (PMID 36559013, 2022).
breast cancer (continued). "The addition of CDK4/CDK6 inhibitors to ET markedly improves progression-free survival (PFS) over ET alone in patients with HR+, HER2− advanced breast cancer (ABC) and has become the new standard of care in this setting." (PMID 34661821, 2022). "In breast cancer, the most extensively studied kinases are CDK4 and CDK6, their interaction with cyclin D can result in cell cycle transition from the G0 to G1 phase." (PMID 35205737, 2022). "The ATP-competitive small molecule compound palbociclib inhibits the enzymatic functions of CDK6 and CDK4 and has been FDA approved for the treatment of breast cancer patients." (PMID 35326705, 2022). "CDK6 increases vascular endothelial growth factor A (VEGF-A) and c-Jun, promoting angiogenesis to allow the promotion of breast cancer progression and CDK4/6I resistance." (PMID 36358806, 2022). "With the development of breast cancer therapy, the clinical application of abemaciclib has been considered a commonly used means due to its significant inhibitory effect on CDK4 and CDK6." (PMID 36226863, 2022). "The CDKIs that are currently FDA-approved for breast cancer therapy are oral agents that selectively inhibit CDK4 and CDK6, include palbociclib (Ibrance), ribociclib (Kisqali), and abemaciclib (Verzenio)." (PMID 36358806, 2022). "High CDK4 and CDK6 expression were also observed in CDK4/6 inhibitors (CDK4/6i)-resistant glioblastoma multiforme xenograft and ER+ breast cancer cell line models separately." (PMID 35327487, 2022). "Another lncRNA frequently expressed in breast cancer, YIYA, interacts with cyclin-dependent kinase 6 (CDK6) and stimulates cell proliferation by increasing the glycolytic pathway; the expression of YIYA is an indicator of poor disease-free survival." (PMID 34298698, 2021). "For instance, knockdown of CDK4 in the mouse model of NSCLC results in the CDK6-induced expression of mutant K-Ras and CDK4/6 inhibitor treatment in breast cancer cells results in the amplification of CDK6 through a feedback mechanism." (PMID 34771669, 2021). "Meta-analysis of various breast cancer gene expression datasets using bc-GenExMiner and the TCGA database further demonstrated a significant positive correlation between ICAM1 with CDK6 mRNA levels." (PMID 34381029, 2021). "This suggests that altered cell cycle machineries, such as the increased expression of CDK6, plays a role in the acquisition of resistance to CDK4/6 inhibitors in some breast cancers." (PMID 32860163, 2021). "Palbociclib, an inhibitor of CDK4 and CDK6, was approved by the FDA in 2015 for the treatment of breast cancer." (PMID 34211613, 2021). "Recently, we found that co-targeting CDK2, CDK6, and ER signaling inhibits the growth of ER+/HER2− breast cancer cells resistant to combined CDK4/6i and ET, supporting the use of this triple combination as a novel therapeutic strategy." (PMID 34771560, 2021). "Remarkably, employment of D 4476 potentiates the efficacy of ribociclib in inhibiting RB1 phosphorylation in multiple CDK4/6i resistant breast cancer cells, accompanied with antagonizing CDK4/6i treatment induced CDK6 protein accumulation." (PMID 34508104, 2021). "Luminal breast cancer that received AKT inhibitor therapy can acetylate FOXO3a, which recognizes BRD4 and then recruits it to the CDK6 gene promoter and induces its transcription." (PMID 34834420, 2021). "RP11–480I12.5 was reported to promote breast cancer growth and tumorigenesis by inhibiting mir-29c-3p mediated degradation of AKT3 and CDK6." (PMID 34026852, 2021). "Moreover, we identified for the first time a c-myc/miR-29b-3p/CDK6 axis in breast cancer that could be responsible for c-myc-induced palbociclib insensitivity, in which c-myc activation resulted in downregulation of miR-29b-3p, further activated CDK6 and inhibited cell-cycle arrest at G1 phase." (PMID 32934206, 2020).
breast cancer (continued). "CDK6 was hyper-hydroxymethylated in HPV(−) tumors at seven intronic regions, is targeted in the treatment of certain breast cancers and recently showed response in the treatment of oral squamous cell carcinoma." (PMID 33203436, 2020). "To test the generality of the synergy, we knocked down CDK1/CDK4/CDK6 in cell lines derived from different cancer types, including A549 (non-small cell lung cancer) and MCF7 (ER+ breast cancer), and treated them with metformin." (PMID 32811807, 2020). "In MCF7 breast cancer cells, Parkin is reported to regulate the mRNA levels of CDK6 (cyclin-dependent kinase 6), which leads to cell cycle arrest and growth inhibition." (PMID 31753025, 2019). "mTOR is targeted by everolimus (along other small molecules; approved by FDA in breast cancer treatment) and is also one of the few intracellular proteins targeted by FDA-approved small molecule drugs (along with CDK4/CDK6 and PARP enzyme)." (PMID 31681603, 2019). "For instance, TNFα signaling induces cdk6 gene expression in Michigan Cancer Foundation 7 (MCF7) cells, a human breast cancer cell line." (PMID 30513680, 2018). "The correlations between mutational status and response to CDK4/6 inhibition are also clear in breast cancer, where downregulation of CDKN2A and amplification of CDK4 or CDK6 were correlated with sensitivity to CDK4/6 inhibition." (PMID 29644000, 2018). "Resistant cells were sensitised to the CDK4/CDK6 inhibitor palbociclib, which is currently approved for therapy of certain breast cancers and, like other CDK4/CDK6 inhibitors, is undergoing clinical trials for other types of cancer." (PMID 29222471, 2017). "In human breast cancer MDA-MB-231 cells, (−)-oleocanthal induces G1/M arrest by modulating the expression of CDK6, cyclin D1, p21, and p27 and induces cell apoptosis by activating the caspase pathway." (PMID 27259268, 2016). "Our data showed that Nar differentially downregulated the expression of Cdk4, Cdk6, and Cdk7 in the human colorectal cancer cell lines SW1116 and SW837 and in the human breast cancer cell lines HTB26 and HTB132." (PMID 26074733, 2015). "Of note, a combined cdk4/cdk6 inhibitor, palbociclib, recently received “breakthrough therapy” status for the treatment of ER+/HER2- breast cancer." (PMID 26029996, 2015). "A miR-191 dependent repression of protein level was shown for NDST1 in MGC803s, CDK6 and SATB1 in human epidermal keratinocytes, and CCND2, CSDA, and EGR1 in the human breast cancer cell line MDA-MB-231." (PMID 25992613, 2015). "It had been confirmed that GLK triterpenes both concentration- and time-dependently mediate G1 cell cycle arrest and significantly decrease the protein level of CDK2, CDK6, cycle D1, p-Rb and c-Myc in MCF-7 human breast cancer cells." (PMID 23966082, 2013). "miR-22 is a tumor suppressor that induces cellular senescence (by targeting CDK6, SIRT1 and Sp1) and is frequently downregulated in ER+ breast cancer." (PMID 24146960, 2013). "miR-195 was shown to inhibit cyclin D1 in HCC and breast cancer, CCND3 in glioblastoma, CDK4 in bladder cancer, CDK6 in HCC, E2F3 in HCC and glioblastoma, BCL-2 in breast and colorectal cancer, RAF1 in breast cancer, and GLUT3 in bladder cancer." (PMID 23335942, 2012). "We interrogated a large clinical cohort of patients with breast cancers which received tumor sequencing using the FDA-cleared, tumor-normal, MSK-IMPACT assay, which provides sequencing coverage spanning the CDK4 and CDK6 exonic regions." (PMID 41279360, 2025). "In addition, amplification events are more common with CDK4 than CDK6 in primary luminal breast cancers: about 6% of luminal tumors carry CDK4 amplification, whereas CDK6 amplification is undetectable." (PMID 41226361, 2025). "Breast cancer cell lines (MCF-7 and T47D) exhibited a significant decrease in p21 and miR3619-5p levels, along with an increase in cyclin D1 and cyclin-dependent kinase 6 (CDK6) expression." (PMID 39641053, 2024).
breast cancer (continued). "In this study, we examined a mathematical model of breast cancer (BC) treatment that combines an oral oestrogen receptor inhibitor, AZD9496 with Palbociclib, a selective inhibitor of cyclin- dependent kinases CDK4 and CDK6." (PMID 38225243, 2024). "Hence, it is interest to document the molecular docking analysis of SR9009 (a pyrrolederivatives) with different breast cancer target protein targets such as HER2, Erα, PR, PI3K, AKT, Reverbα, BRMS1, Aromataseand mTOR, CDK4, CDK6, TK and Top II." (PMID 40230904, 2024). "Furthermore, a recent investigation on breast cancer demonstrated that miR-34c targets CCND1, CDK4, and CDK6, pivotal cell cycle regulators that prompt arrest at the G2/M stage." (PMID 39097731, 2024). "Moreover, we found six sex-biased genes (EGFR, CDK6, PRKCB, PDCD1, KCNH2, FCGR3B, and TOP2A) in BRCA were the therapeutic targets of breast cancer." (PMID 39175079, 2024). "In abemaciclib-resistant breast cancer, p18INK4c is associated with CDK6 but not with CDK4 and impairs binding of abemaciclib to CDK6 thus rendering it active." (PMID 38561743, 2024). "Consequently, inhibiting CDK4/CDK6 can enhance the tumor-suppressive function of RB1, as demonstrated in breast cancer treatment." (PMID 39664374, 2024). "Palbociclib, a CDK6 inhibitor, was recently approved by the FDA for treating breast cancer." (PMID 37444412, 2023). "Thus, in clinical practice, inhibition of CDK4 and CDK6 has been an effective way of treating advanced HR+, HER2- breast cancer." (PMID 37296790, 2023). "A recent study declared that CDK4/CDK6 inhibitors (8, 9, and 10) might impede SARS-CoV-2 infection in breast cancer females." (PMID 36851782, 2023). "In breast carcinoma cells, viability and clonogenicity were negatively affected upon PSMD2 repression, cells were arrested in G0/G1 phase, and the level of the proteins involved in the progression of the cell cycle (CDK6 and CCND1) was significantly decreased." (PMID 37529110, 2023). "CDK4/CDK6 inhibitors, which are well established for the treatment of breast cancer, have not previously been analyzed in the context of SM." (PMID 35804842, 2022). "In this review, it was noted that three in vitro studies (4.4%) reported that carvacrol decreased CDK4 protein expression in human tongue squamous cell carcinoma (Tca-8113 cells) and in breast cancer (MCF-7 cells) and only one (1.4%) reported a decrease in CDK6 in MCF-7 cells." (PMID 34305611, 2021). "Consequently, CDK6 protein abundance was decreased in the context of silencing of CK1ε in MDA-MB-231 and MCF7 breast cancer cells." (PMID 34508104, 2021). "CDK4 and CDK6, therefore, emerged as viable therapeutic targets, and evaluation of CDK4 and 6 inhibitors in combination with other therapies is an area of active investigation that is changing the treatment landscape for HR+, HER2- advanced breast cancer." (PMID 35223458, 2021). "Moreover, a flavone compound from Urginea indica bulbs tends to stimulate apoptosis, G0/G1phase arrest, and also inhibits angiogenesis in breast cancer cells by restricting CDK1 and CDK6." (PMID 34361615, 2021). "Notably, in keeping with previous reports, we found that CDK6 silencing was the top scoring genetic event for enhancing efficacy of CDK4/6i, and RB1 depletion was the top hit for promoting resistance in breast cancer cells to CDK4/6i." (PMID 34508104, 2021). "Although mutations in the kinase domain of CDK4 and CDK6 have not been reported as mechanisms of resistance to CDK4/6i, CDK6 amplification was described in CDK4/6i-resistant breast cancer cell models." (PMID 34771560, 2021). "Alternatively, ER+/HER2− breast cancers may be treated with cyclin-dependent kinase CDK4 and CDK6 inhibitors (e.g., palbociclib, abemaciclib or ribociclib)." (PMID 32878084, 2020). "In addition, in the case of breast cancer, the lncRNA LINC00538 (YIYA) was expressed in ~40% of cases and correlated with cyclin-dependent kinase 6 (CDK6) expression and unfavorable survival outcomes." (PMID 32765426, 2020).